ACHE (acetylcholinesterase (Yt blood group))
Diseases named in the same sentence as ACHE in open-access papers (continued):
Sharing a sentence is not in itself a finding about the gene and the disease.
Alzheimer disease (continued). "Inhibiting the enzyme acetylcholinesterase (AChE), which breaks down ACh, is a viable technique for treating people with Alzheimer’s disease." (PMID 36594059, 2023). "Inhibitors of AChE and BChE have found application as drugs developed for the treatment of Alzheimer’s disease which is a neurodegenerative disorder characterized by the loss of memory and consciousness." (PMID 36829813, 2023). "According to the obtained results, O. sancta extracts greatly reduced AChE activity, suggesting their potential use in treating Alzheimer’s disease." (PMID 37374193, 2023). "Several plants contain secondary metabolites with antioxidant and anti-AChE properties, which can slow the progression of Alzheimer’s disease by inhibiting AChE activity and protecting neurons from oxidative damage." (PMID 37893530, 2023). "As the tested structures showed drastically better inhibition of the BchE than AchE, these results are very important as BchE has been attracting growing attention due to its positive role in Alzheimer’s disease." (PMID 37175190, 2023). "Computational approaches suggest that THCV, Cannabinol C2, and Cannabidiorcol are more appropriate for the inhibition of the enzymes AChE and BuChE, which act as the culprits of Alzheimer’s disease." (PMID 36771595, 2023). "The key enzymes involved in Alzheimer’s disease pathways are acetylcholinesterase (AChE) and butyrylcholinesterase (BuChE)." (PMID 37049419, 2023). "For example, compounds endowed with MAO-B as well as AChE and BuChE inhibitory activities have been proposed as useful candidates for Alzheimer’s disease treatment." (PMID 38136164, 2023). "In another experimental study, usnic acid was shown to have inhibitory activity against the acetylcholinesterase (AChE) enzyme, which is the target for the treatment of Alzheimer’s disease." (PMID 37512512, 2023). "The clinical uses of AChE inhibitors include treatment of Alzheimer’s disease, glaucoma and myasthenia gravis." (PMID 37241886, 2023). "To date, three of the four medications for treating Alzheimer’s disease that have been authorized were from AChE inhibitor development programs." (PMID 37049419, 2023). "The inhibitory activities of the herbal extracts were assessed on the key enzymes that control the occurrence of some NCDs including type II diabetes (T2DM) (α-amylase and α-glucosidase), Alzheimer’s disease (AChE, BChE, and BACE-1) and hypertension (ACE)." (PMID 38066118, 2023). "Natural chalcones have been found to possess a small molecular weight and a lower toxicity profile compared to the other AChE inhibitors, making them a more attractive option for the treatment of Alzheimer’s disease." (PMID 37110646, 2023). "Considering its importance in cholinergic system modulation, acetylcholinesterase (AchE) has become a prime therapeutic target in the treatment of Alzheimer’s disease (AD)." (PMID 36985531, 2023). "Monoamine oxidase-B (MAO-B), acetylcholinesterase (AChE), and butyrylcholinesterase (BChE) have been considered target enzymes of depression and neurodegenerative diseases, including Alzheimer’s disease (AD)." (PMID 36678580, 2023). "Many therapeutic drugs for treating different diseases, such as Alzheimer’s disease (AD), insecticides, and chemical warfare agents, have been synthesized for targeting the inhibition of acetylcholinesterase (AChE)." (PMID 37959813, 2023). "Donepezil, a drug for Alzheimer’s disease (AD) was used as the standard AChE inhibitor which showed an IC50 of 7.11 ± 0.24 μg/mL." (PMID 36677851, 2023). "Acetylcholinesterase (AChE) enzymes play an essential role in the development of Alzheimer’s disease (AD)." (PMID 36770702, 2023). "It was known that high BChE levels are interconnected with the distinctive neuropathologic characteristic of Alzheimer’s disease (AD) and that both enzymes BChE and AChE are pharmacologically appropriate targets in neurodegenerative disorders." (PMID 37175190, 2023).
Alzheimer disease (continued). "Current research study is strong evidence for the inhibition of AChE ultimately helpful for the cure of Alzheimer’s disease in future after conducting further studies." (PMID 35239683, 2022). "The central-acting AChE inhibitors, which include donepezil and galantamine, have been used to treat Alzheimer’s disease (AD)." (PMID 35725377, 2022). "Although these drugs can delay disease progression, most of them are accompanied by certain side effects Therefore, the screening of AChE inhibitors from natural products has become a research hotspot to better treat Alzheimer’s disease." (PMID 36388527, 2022). "In one study, silibinin was found to be a dual inhibitor of AChE and Aβ peptide aggregation, implying a therapeutic method for treating Alzheimer’s disease." (PMID 35205079, 2022). "Modern pharmacological studies have proven that this drug has a positive therapeutic potential on Alzheimer’s disease, and several alkaloids have been identified as the main AChE inhibitors." (PMID 36388527, 2022). "Our study proposes the examination of CP, SCOP, and CP + SCOP as potential AChE inhibitors for their ability to modulate cognitive deficits in Alzheimer’s disease." (PMID 35212831, 2022). "The AChE inhibiting action of AHE depicts the potential of this plant in the treatment of Alzheimer’s disease as well." (PMID 35790919, 2022). "Considering the multifactorial pathogenesis of Alzheimer’s disease, we continuously exploit multifunctional agents that can simultaneously inhibit AChE and BChE and exert antioxidant effects." (PMID 36232533, 2022). "And increasing acetylcholine levels with acetylcholinesterase (AChE) inhibitors is currently one of the most effective strategies for the treatment of Alzheimer's disease." (PMID 35958258, 2022). "In the late stages of the Alzheimer’s disease, BChE plays a more important role in comparison to AChE." (PMID 36500605, 2022). "The administration of BC at a dose of 2.05 mg/kg inhibited the increase in AChE activity in STZ-induced Alzheimer’s disease in mice." (PMID 35807538, 2022). "In the studies of AChE inhibition, which is very important in Alzheimer’s disease, it was found that the effectiveness of AChE inhibition was increased as the number of PDOPA coatings on HNT increased." (PMID 36297924, 2022). "Saffron had shown about 30% inhibitory effect on acetylcholinesterase (AChE) activity, which can be another mechanism for treating Alzheimer's disease." (PMID 35198096, 2022). "One of the symptoms of Alzheimer’s disease (AD) is low acetylcholine level due to high acetylcholinesterase (AChE) activity." (PMID 35745206, 2022). "Natural AChE inhibitors have recently attracted more interest for the treatment of the symptoms of Alzheimer’s disease." (PMID 36388527, 2022). "Because the major enzyme in the pathogenesis of Alzheimer’s disease is AChE, the suppression of AChE raises the signal transfer in cholinergic pathways and decreases the symptoms of Alzheimer’s disease." (PMID 35204266, 2022). "AChE activity is dominant in regulating acetylcholine levels in healthy brains, while in an Alzheimer’s disease (AD) patient’s brain, the activity of BuChE is increased." (PMID 36080382, 2022). "The anticholinesterase activity of seaweed extracts has been tested against acetylcholinesterase (AChE) and butyryl cholinesterase (BChE), which are the main enzymes of Alzheimer’s disease." (PMID 35200670, 2022). "Flavonoids are promising natural products with neuroprotective potential that prevent or slow the progression of Alzheimer disease via the inhibition of key enzymes such as AChE, BChE and BACE-1 (Beta-site APP Cleaving Enzyme-1)." (PMID 36295014, 2022). "Several compounds were identified as potential acetylcholinesterase (AChE) or butyrylocholinesterase (BChE) inhibitors in the search for potential drug candidates for treating Alzheimer’s disease." (PMID 36297331, 2022).
Alzheimer disease (continued). "It has been proved that the inhibition of AChE enzyme, which catalyses the breakdown of ACh, is a useful therapeutic approach for the symptomatic treatment of Alzheimer’s disease." (PMID 35200670, 2022). "The objective of this study was to design new polysubstituted pyrrole derivatives as selective acetylcholinesterase (AChE) inhibitors to target Alzheimer's disease." (PMID 36075926, 2022). "TLC-AChE inhibition detects AChE inhibitors (AChEI), which are currently the best form of pharmacotherapy of Alzheimer’s disease." (PMID 35408515, 2022). "Donepezil, also referred to in early publications as ‘E2020’, is a piperidine inhibitor of acetylcholinesterase (anti‐AChE) that has been widely prescribed for mild to moderate dementia in Alzheimer's disease (AD)." (PMID 36028305, 2022). "We also determined the anti-AChE activity of huperzine A, which is used as a positive control drug to treat Alzheimer’s disease." (PMID 36388527, 2022). "The inhibition of AChE due to EO is of relevant interest in the treatment of Alzheimer disease since different studies report in vitro and clinical AChE inhibitory activity." (PMID 35161347, 2022). "The most successful way and major goal for treating Alzheimer's disease is to diminish acetylcholine levels by using transitory inhibitors to block the cholinesterase that AChE and BuChE catalyze." (PMID 36578633, 2022). "Recent studies have demonstrated that in the normal brain, AChE activity predominates over the BuChE activity while, with the progression, for example, of Alzheimer’s disease (AD), brain levels of BuChE increase and AChE activity is maintained or decreases." (PMID 36365414, 2022). "It is equally important to establish if the prospective AChE inhibitors identified in this study can be optimized for the treatment of diseases resulting from low levels of acetylcholine, such as Alzheimer's disease." (PMID 35873645, 2022). "Different varieties of honey have been reported to act as a potential natural source of acetylcholinesterase (AChE) inhibitors in Alzheimer’s disease." (PMID 35630774, 2022). "Others, such as galantamine, extracted from the TCM herb Lycoris radiata, is a licensed acetyl cholinesterase (AChE) inhibitor for Alzheimer’s disease treatment in Europe (Li and Zhang, 2009)." (PMID 36440293, 2022). "The multi-level effect of the raw material has been additionally confirmed by demonstrating that the inhibition of AChE and BChE translates into the nervous system’s response can be used, for example, in the treatment of Alzheimer’s disease." (PMID 35408722, 2022). "In summary, this study provided new small molecules of AChE and COX inhibitors with good therapeutic potential for neurological disorders such as Alzheimer's disease and other causes of dementia." (PMID 35815566, 2022). "Acetylcholinesterase (AChE) inhibitors, both natural and synthetic, increase the cholinergic tone in the brain and are beneficial in Alzheimer's disease and cognitive enhancement." (PMID 35599726, 2022). "Galantamine, an isoquinoline alkaloid from Amaryllidaceae, is certainly a well-known example of a drug introduced to the therapeutic strategies in the treatment of the symptomatic Alzheimer’s disease (AD) as an acetylcholinesterase (AChE) inhibitor." (PMID 35563248, 2022). "Compound 7 demonstrated its predicted activity towards binding inhibition of AChE enzyme and Alzheimer’s disease due to higher hydrophilicity, a larger topological polar surface area, and a strong H-bonding acceptor." (PMID 37621349, 2022). "For prospective benefits in Alzheimer’s disease, a variety of thiazole acetamides were produced and screened for invitro butyryl cholinesterase (BChE) and acetyl cholinesterase (AChE) inhibitory activity (AD)." (PMID 35807236, 2022). "Many human metabolic SHs have been pursued as promising drug targets for human diseases, such as AChE for Alzheimer’s disease." (PMID 36105595, 2022).
Alzheimer disease (continued). "AchE inhibition is an auspicious plan of action against Alzheimer’s disease, myasthenia gravis, Parkinson’s disease, senile dementia and ataxia." (PMID 35807565, 2022). "In an Alzheimer’s-disease (AD) brain, BuChE activity rises, while AChE activity remains unchanged or declines." (PMID 35744919, 2022). "For decades, the research on AChE inhibitors has been an area of interest for its role in the management of Alzheimer’s disease, and most of the drugs approved by Food and Drug Administration are AChE inhibitors." (PMID 35956919, 2022). "As acetylcholinesterase (AChE) plays a crucial role in advancing Alzheimer’s disease (AD), its inhibition is a promising approach for treating AD." (PMID 36678724, 2022). "Although the role of AChE in Alzheimer’s disease is unclear, it is by far the most viable therapeutic target for improving symptoms of the disease." (PMID 36296686, 2022). "The alteration of cholinergic systems is involved in many neurodegenerative disorders, including Alzheimer’s disease, hence a huge effort has been devoted over the decades to discovering and developing AChE inhibitors that can contrast cognitive impairment." (PMID 35563466, 2022). "We also investigated, in silco, the molecular modeling of our nucleoside as a binding inhibition of AChE enzyme towards the advancement of an efficient drug against Alzheimer’s disease." (PMID 37621349, 2022). "A natural product named Huperzia serrata was also found to inhibit the activity of the enzyme AChE in mice models of Alzheimer’s disease and further ameliorated the impairment of cognition." (PMID 35956919, 2022). "Usually, the activity of AChE is reduced in the brain of patients suffering with Alzheimer’s disease, but his concentration is enhanced after binding to the plaques of Aβ." (PMID 35956919, 2022). "As butyrylcholinesterase (BChE) plays a role in the progression of symptoms and pathophysiology of Alzheimer’s disease (AD), selective inhibition of BChE over acetylcholinesterase (AChE) can represent a promising pathway in treating AD." (PMID 36297332, 2022). "Alzheimer’s Disease (AD) is characterized by a progressive cholinergic neurotransmission imbalance, with a decrease of acetylcholinesterase (AChE) activity followed by a significant increase of butyrylcholinesterase (BChE) in the later AD stages." (PMID 36678552, 2022). "Type-2 diabetes mellitus (T2DM) and Alzheimer’s disease (AD) have shared abnormal levels of the enzymes: acetylcholinesterase (AChE) and butyrylcholinesterase (BuChE)." (PMID 36297317, 2022). "Compounds with structural similarities to the neurotransmitter (acetylcholine) are mostly used to inhibit the activity of acetylcholinesterase (AChE) in Alzheimer’s disease (AD) therapy." (PMID 36337665, 2022). "Although no cytotoxic activity was noticed against human colon cancer and human lung cancer, LFD showed 24.04% inhibition against BChE and 60.30% inhibition against AChE and is therefore beneficial for Alzheimer’s disease (AD)." (PMID 36080247, 2022). "Acetylcholinesterase (AChE) is one of the classical targets in the treatment of Alzheimer’s disease (AD)." (PMID 35630613, 2022). "Subsequent surveys have determined the relevance of both BChE and AchE in the pathophysiology of Alzheimer’s disease and have demonstrated the therapeutic benefit of the inhibition of both BchE and AchE." (PMID 34679706, 2021). "A number of recent studies have investigated various modifications of sulfonamides, for example, multitarget agents for the inhibition of AChE enzyme, multifunctional agents for Alzheimer’s disease, and/or an in vivo active reversible BChE inhibitor." (PMID 34502357, 2021). "Inhibitors of AChE enzyme are clinically used in Alzheimer’s disease to improve memory and cognition and are the only approved agents by the FDA for the disease in addition to mementine-a glutmate receptor antagonist." (PMID 34588850, 2021).
Alzheimer disease (continued). "Several series of simple 3-phenylcoumarins have been studied to prevent and treat Alzheimer’s disease and its complications, showing high activity toward AChE and MAO, together with antioxidant activity." (PMID 34771164, 2021). "Inhibition of AChE, the key enzyme in the breakdown of acetylcholine, is considered one of the treatment strategies against Alzheimer’s disease." (PMID 34692640, 2021). "LF458, is the first oxaphenalenone with potent AChE inhibitory activity, signifying its potential for further research against Alzheimer’s disease." (PMID 35003004, 2021). "Riluzole has neuroprotective effects on Alzheimer’s disease in rat models, due to decreased acetylcholinesterase (AChE) activity and oxidative stress marker." (PMID 34573888, 2021). "Recent studies have focused on explaining the basis of the interaction between CBD and acetylcholinesterase (AChE), a key enzyme in the pathogenesis of Alzheimer’s disease." (PMID 33919010, 2021). "Inhibiting AChE to restore acetylcholine levels is an effective treatment for senile dementia (such as Alzheimer’s disease, vascular dementia, Parkinson’s disease, or physical and cognitive symptoms associated with multiple sclerosis and Down syndrome)." (PMID 34361800, 2021). "The inhibition of BuChE and AChE is of great interest for the study of the treatment and slowing down of Alzheimer’s disease and other neurodegenerative diseases." (PMID 34071744, 2021). "In our recently published work, an extensive in silico approach was used to identify cost-effective AChE inhibitors for treating Alzheimer’s disease." (PMID 35126145, 2021). "These enzymes which are key enzymes were intervening in some human pathologies such as diabetes for α-amylase, neurodegenerative disorders such as Parkinson’s disease for tyrosinase and Alzheimer’s disease for AChE and BChE." (PMID 34579487, 2021). "It is a promising pharmaceutical ingredient for developing acetylcholinesterase (AChE) reversible inhibitors in the treatment of Alzheimer’s disease." (PMID 34222213, 2021). "One of the most successful strategies to target Alzheimer’s disease is the development of agents that effectively interact with key enzymes involved in cholinergic dysfunction, especially acetylcholinesterase (AChE)." (PMID 34832886, 2021). "Emerging of the dual Acetylcholinesterase (AChE)/Butyrylcholinesterase (BuChE) inhibitors has increased for treating Alzheimer disease." (PMID 33869871, 2021). "Acetylcholinesterase (AChE) inhibitors have been commonly used to delay the progression of Alzheimer’s disease (AD), one of the most common forms of neurodegenerative disorders characterized by progressive degeneration of cholinergic neurons." (PMID 34500749, 2021). "In Alzheimer’s disease, Avarol derivatives (such as thiosalycil-prenyl-hydroquinones) act as competitive acetylcholinesterase (AChE) inhibitors and show good neuroprotection." (PMID 34514163, 2021). "The daily oral administration of acetylcholinesterase (AChE) inhibitors for Alzheimer’s disease features low patient compliance and can lead to low efficacy or high toxicity owing to irregular intake." (PMID 34208289, 2021). "The protective effect of GAL on mild to moderate Alzheimer’s disease is due to its inhibitory effect on AChE, which was confirmed in the present study by the 16% reduction in AChE activity in mice brain homogenates." (PMID 33806197, 2021). "In SH‐SY5Y and mouse primary cells, we have demonstrated that an increased phosphorylation of tau by kinase GSK3β, as occurs in Alzheimer disease, can modulate the levels and enzymatic activity of cholinergic AChE." (PMID 32955735, 2021). "By inhibiting AChE of the cholinergic synapse, AChE inhibitors enhance acetylcholine levels by inhibiting AChE of the cholinergic synapse thus enhancing the function and relieving the symptoms of neurological illnesses, including Alzheimer’s disease." (PMID 34692640, 2021).